TGDS (TDP-glucose 4,6-dehydratase)
Description:
UDP-glucose 4,6-dehydratase that converts UDP-glucose into UDP-4-keto-6-deoxyglucose, and which is required for glycosaminoglycan biosynthesis and skeletal development. UDP-4-keto-6-deoxyglucose is a mimic of the reaction intermediate of UXS1 and acts as an enzyme-rescue metabolite to promote the completion of UXS1 catalytic cycle when NAD(+) levels are low. Under low NAD(+) conditions, UXS1 forms an inactive UDP-4-ketoxylose intermediate bound to NADH, impairing the synthesis of specific glycans that are essential for skeletal development. UDP-4-keto-6-deoxyglucose is used by the inactive NADH-bound UXS1 to produce UDP-6-deoxyglucose and NAD(+) within the catalytic pocket of UXS1, regenerating the essential cofactor NAD(+).
Synonyms: TDPGD; SDR2E1; CATMANS
Tractability: PROTAC: ubiquitination databases record sites on it.
Gene: Protein-coding gene on chromosome 13 (94,574,054 to 94,596,276, reverse strand). Ensembl gene ENSG00000088451.
Subcellular location: Endoplasmic reticulum; Golgi apparatus
Subcellular location (Human Protein Atlas): Nucleoplasm; Cytosol; Nucleoli
Gene Ontology:
Molecular function: dTDP-glucose 4,6-dehydratase activity; protein binding; UDP-glucose 4,6-dehydratase activity; hydro-lyase activity
Biological process: glycosaminoglycan biosynthetic process; nucleotide-sugar metabolic process
Cellular component: endoplasmic reticulum; Golgi apparatus
Genetic constraint (gnomAD): Loss-of-function variants: 17 observed, 21.53 expected, observed/expected ratio (o/e) 0.79, 90% interval 0.54 to 1.18. The upper end of that interval is the gene's LOEUF score, 1.18, which puts it in group 5 of 6, group 1 being the genes least tolerant of losing a copy. Missense variants: 209 observed, 244.12 expected, observed/expected ratio (o/e) 0.86, 90% interval 0.76 to 0.96. Synonymous variants: 69 observed, 87.03 expected, observed/expected ratio (o/e) 0.79, 90% interval 0.65 to 0.97.
Gene-disease validity (ClinGen):
ClinGen rates the evidence that TGDS causes each of these diseases.
Catel-Manzke syndrome (autosomal recessive): Definitive. Catel-Manzke syndrome is a rare bone disease characterized by bilateral hyperphalangy and clinodactyly of the index finger typically in association with Pierre Robin sequence comprising micrognathia, cleft palate and glossoptosis.
Homologues: Orthologues: chimpanzee TGDS (99% identical), macaque TGDS (99% identical), rabbit TGDS (97% identical), pig TGDS (95% identical), guinea pig TGDS (94% identical), mouse Tgds (91% identical), rat Tgds (91% identical), dog TGDS (84% identical), tropical clawed frog tgds (64% identical), Caenorhabditis elegans bus-5 (35% identical), Drosophila melanogaster CG7724 (20% identical). Paralogues in human: HSD3B1 (23% identical), HSD3B2 (23% identical), SDR42E1 (23% identical), UXS1 (23% identical), SDR42E2 (21% identical), GALE (20% identical), HSD3B7 (19% identical), NSDHL (18% identical), GFUS (15% identical), GMDS (15% identical).
Diseases named in the same sentence as TGDS in open-access papers:
TGDS is named in the same sentence as 10 diseases in open-access papers, as found by Europe PMC text mining. Sharing a sentence is not in itself a finding about the gene and the disease. The quoted sentences say what the papers report.
Catel-Manzke syndrome (7 papers, 2021 to 2025). "We obtained fibroblasts from three controls and five individuals with Catel–Manzke syndrome due to biallelic variants in TGDS." (PMID 40836090, 2025). "Together, the KI/KO mouse model recapitulates important clinical aspects of Catel–Manzke syndrome, corroborates the biochemical function of TGDS and provides evidence that a functional UXS1 deficiency might underlie the clinical phenotype." (PMID 40836090, 2025). "In humans, pathogenic variants in TGDS are associated with the recessive inherited Catel Mankze syndrome (OMIM 616145) that is characterized by bilateral clinodactyly, micrognathia digital syndrome, and in some cases cleft palate and heart malformations." (PMID 39460958, 2024). "Defects in human TGDS lead to Catel–Manzke syndrome, which is characterized by a unique form of hyperphalangy." (PMID 36911920, 2023). "The phenotype of patients with VCRL is overlapping with that of CATMANS (Catel–Manzke Syndrome, CMS) patients which is caused by mutations in the TGDS gene that encodes for TDP-glucose 4,6-dehydratase." (PMID 34200361, 2021). "Catel-Manzke syndrome (CMS) is a rare genetic disorder associated with mutations in the TDP-glucose 4,6-dehydratase (TGDS) gene, the function of which in vertebrates remains unclear." (PMID 41159851, 2025). "This work reveals the molecular link between TGDS, UXS1, H6PD and Catel–Manzke syndrome." (PMID 40836090, 2025).
colorectal cancer (2 papers, 2010 to 2025). A primary or metastatic malignant neoplasm that affects the colon or rectum. "Ten of these genes (WDR67, RFXAP, RP11-50D16.3, CAB39L, THSD1, SPRY2, TGDS, CLDN10, SLC10A2, CD33L3) have been reported changed in tumor tissues, while only 2 (RP11-50D16.3, SLC10A2) have been reported to appear changed in colorectal cancer." (PMID 20467480, 2010).
amelogenesis imperfecta (1 paper, 2021). Amelogenesis imperfecta (AI) represents a group of developmental conditions affecting the structure and clinical appearance of the enamel of all or nearly all the teeth in a more or less equal manner, and which may be associated with morphologic or biochemical changes elsewhere in the body. "Even if few features are typical for some disorders, characteristic hand anomalies in CANT1, IMPAD1, CHSY1, and TGDS-related conditions or amelogenesis imperfecta in dysplasia due to mutations in SLC10A7, for example, may help clinicians to orientate the clinical diagnosis." (PMID 34220933, 2021).
glioblastoma (1 paper, 2025). The most malignant astrocytic tumor (WHO grade IV). "Importantly, our analysis also identified differential expression of TGDS (TDP-glucose 4,6-dehydratase), extending beyond the established gene signatures associated with glioblastoma progression and immune microenvironment." (PMID 41275376, 2025). "The functional role of TGDS in human glioblastoma pathophysiology remains unexplored, presenting a novel candidate for further mechanistic investigation in GBM biology." (PMID 41275376, 2025).
TGDS also shares sentences with these, for which no sentence is quoted: heart malformations (2 papers); tumor (2); genetic disorder (1); hyperphalangy (1); lung carcinoma (1); osteosarcoma (1).